SELENBP1 (selenium binding protein 1)
Diseases named in the same sentence as SELENBP1 in open-access papers (continued):
Sharing a sentence is not in itself a finding about the gene and the disease.
tumor (continued). "Consistently, reduction of SELENBP1 expression was also frequently observed in a majority of tumor tissues from TCGA-BLCA cohort (p < 0.0001)." (PMID 31918717, 2020). "The overall pattern of the Western blot is consistent with immunohistochemistry of the tumor tissue array in that SELENBP1 Western blot bands of tumor arrays tended to be more intensive than those of the matched non-tumor array." (PMID 32443734, 2020). "Our finding, in terms of the decrease of SELENBP1 in tumor tissues, is consistent with the previous reports that described the suppression of SELENBP1 in diverse types of epithelial cancers (details in introduction)." (PMID 32443734, 2020). "It was clear that normal samples cluster towards higher SELENBP1 expression than tumor tissues (Wilcoxon rank-sum test, p = 9.01e−7)." (PMID 31918717, 2020). "In our study, levels of SELENBP1 were significantly decreased in liver tumor tissues as compared with matched non-tumor (counterpart normal) liver tissues." (PMID 32443734, 2020). "SELENBP1 (selenium-binding protein 1) has already been described as a tumor suppressor involved in the regulation of cell proliferation, senescence, migration, and apoptosis." (PMID 30941304, 2019). "In summary, SELENBP1 influences the tumor microenvironment and SELENBP1 action is functionally influenced by GPX1." (PMID 29535818, 2018). "Some of these targets like SELENBP1 were tested for their presence in tumor tissue using immunoblotting." (PMID 28938569, 2017). "The result indicated that SELENBP1 (−) subgroup has poor OS, tumor recurrence-free survival, and metastasis-free survival of patients with NPC, and has statistically significant." (PMID 27583873, 2016). "The relative expression of SELENBP1 gene in the 2 groups showed that it was lower in tumor than in normal tissue (P < 0.01)." (PMID 27583873, 2016). "The aims of the present study were (a) to compare the expression level of SELENBP1 in the tumor with that in normal adjacent tissue, and (b) to define the value of SELENBP1 expression for predicting tumor outcomes, such as progression and cancer-related death." (PMID 25227434, 2014). "Overall, the Allred score of SELENBP1 expression in normal tissues was 6.69±1.15, with a statistically significant reduction in SELENBP1 expression of 5.37±2.41 in the tumor tissue group (p<0.05)." (PMID 23704933, 2013). "The other proteins which showed decreased expression in the tumor tissue included Selenium-binding protein 1, HMG CoA synthase, 1-Cys peroxiredoxin protein 2, Fcgbp protein, Cytochrome c oxidase, subunit Va, and ETHE1 protein." (PMID 19491504, 2009). "Functional characterization experiments further revealed that SELENBP1 functions as a tumor suppressor: its expression was consistently diminished in LUAD cell lines and tissues, and its knockdown promoted cell proliferation, migration, and resistance to apoptosis." (PMID 40787454, 2025). "The qRT-PCR results revealed pronounced upregulation of TFF1, ITPKA, UBE2C, and IGFBP3, along with marked downregulation of SLC34A2 and SELENBP1 in tumor samples relative to adjacent normal tissues, which was in strong agreement with the transcriptomic profiling outcomes." (PMID 40787454, 2025). "In addition, functional validation experiments confirmed that SELENBP1 plays a tumor-suppressive role, further supporting its relevance as a potential intervention target in LUAD." (PMID 40787454, 2025). "Mechanistically, SELENBP1 was identified and experimentally validated as a putative tumor suppressor that modulates LUAD cell proliferation, migration, oxidative stress, and apoptosis, both in vitro and in vivo, underscoring its potential as a therapeutic target." (PMID 40787454, 2025). "Moreover, the discovery of SELENBP1 as a candidate tumor suppressor emphasizes its importance in guiding both clinical risk categorization and the design of personalized treatment strategies for individuals classified as high-risk LUAD cases." (PMID 40787454, 2025).
tumor (continued). "SELENBP1 is a marker of terminally differentiated epithelial cells in the colon and may act as a tumor suppressor." (PMID 39728443, 2024). "In addition, we also verified that overexpression of SELENBP1 inhibited the growth of tumor cells in vivo, and it was correlated with the inhibition of PI3K/AKT/mTOR pathway." (PMID 37606338, 2023). "It suggested that inhibition of S phase might be correlated with the tumor‐suppressive role of SELENBP1 in NSCLC cells in vitro." (PMID 37606338, 2023). "In a validation study, it was indicated that the biopsy specimens sampled from tumor surface could reflect SELENBP1 expression throughout the entire tumor, despite the heterogeneity within tumors." (PMID 37548833, 2023). "Numerous observations of its suppression in various tumors and its induction during terminal differentiation gave reason to the assumption that SELENBP1 may interfere with cellular proliferation, thus acting as a tumor suppressor." (PMID 37437449, 2023). "SELENBP1 has been designated a tumor suppressor that may inhibit cell proliferation, angiogenesis, metastasis, and resistance to chemotherapy, as well as promote apoptotic cell death." (PMID 37760083, 2023). "Besides, suppression of SELENBP1 was correlated with increased tumor size and unfavorable patient prognosis, which validated the results from previous studies." (PMID 36117772, 2022). "SELENBP1 belongs to selenium-binding proteins and functions as a tumor suppressor." (PMID 36386843, 2022). "To test whether SELENBP1 suppression in CRCs contributed to increased tumor invasiveness, we analyzed the relationships between SELENBP1 expression and clinicopathological variables." (PMID 36117772, 2022). "Then, IHC staining of SELENBP1 in colorectal NTs and CRCs in the HPA database indicated that SELENBP1 was distributed diffusively in the nuclei and cytoplasm and on the membrane, and its expression was significantly lower in tumor cells than in glandular cells (p < 0.0001)." (PMID 36117772, 2022). "A study found that SELENBP1 could inhibit angiogenesis by binding with Dll4 and antagonizing the Dll4/Notch1 signaling pathway in CRC, which made SELENBP1 a potential tumor suppressor." (PMID 36286020, 2022). "In addition, we only confirmed the in vivo tumor-suppressive activity of SELENBP1 using the subcutaneous xenograft model, since the cell lines we used failed to derive liver or lung metastasis." (PMID 36117772, 2022). "In addition, the correlation of SELENBP1 gene with tumor immune infiltration and prognosis was analyzed using ssGSEA, ESTIMATE, tumor immune dysfunction and rejection (TIDE) algorithm and Kaplan-Meier (KM) Plotter database." (PMID 36253721, 2022). "Being a selenium-binding protein, SELENBP1 may duplicate some of the tumor-suppressive roles of selenium (Se), which is an essential trace mineral indispensable to human health." (PMID 36117772, 2022). "Taken together, these observations indicate that SELENBP1 has tumor-suppressive roles in vitro." (PMID 36117772, 2022). "Selenium binding protein 1 (SELENBP1) is frequently downregulated in tumor vessels in CRC." (PMID 36286020, 2022). "SELENBP1 significantly inhibited tumor growth and tumor weight (a–c)." (PMID 36117772, 2022). "Selenium-binding protein 1 (SELENBP1) was previously hypothesized to act as a tumor suppressor, and to be involved in intracellular protein degradation and transport." (PMID 33901808, 2021). "It has been hypothesized that down-regulation of SELENBP1 may contribute to the aberrant proliferation of tumor cells." (PMID 33901808, 2021). "The results showed that overexpression of SELENBP1 induced a significant G0/G1 phase arrest in UMUC3 cells, suggesting that G0/G1 phase arrest induction might be associated with tumor suppressive role of SELENBP1." (PMID 31918717, 2020). "Linear regression analysis was performed on non-tumor and matched tumor tissues to examine the causal relationship between SELENBP1 and HBx." (PMID 32443734, 2020).
tumor (continued). "Therefore, our finding provides valuable information when developing SELENBP1 as a genomic methylation-based biomarker for tumor progression and prognostic outcome." (PMID 31918717, 2020). "The SELENBP1 downregulation mechanism in tumor cells still remains to be identified." (PMID 32443734, 2020). "Moreover, immunohistochemistry on tissue microarrays containing 60 pairs of human liver tissue showed decreased intensity of SELENBP1 in tumor tissues as compared with their matched non-tumor liver tissues." (PMID 32443734, 2020). "As several studies in tumour cells suggest that SELENBP1 counteracts proliferation and dedifferentiation, high SELENBP1 levels may support the maintenance of a well-differentiated phenotype in mature adipocytes." (PMID 30469030, 2019). "SELENBP1 is a marker of terminally differentiated epithelial cells in the colon, and it may act as tumour suppressor." (PMID 30469030, 2019). "Indeed, SELENBP1 is described as a tumor suppressor in these tumor types, since decreased levels are associated with enhanced cell proliferation and migration, as well as inhibited apoptosis." (PMID 29535818, 2018). "Analysis of pathological section concluded that SELENBP1 in the majority of HNSCC is low expression and in cancer nests is lower expression than surrounding normal tissue, even associated with the malignant degree of tumor." (PMID 27583873, 2016). "We also analyzed the relationship between SELENBP1 expression and tumor N-stage, T-stage, and tumor grade, as a result has nothing to do, so indicating that SELENBP1 expression does not reflect the degree of cancer development, and it is consistent with analysis of GEO data." (PMID 27583873, 2016). "SELENBP1 mRNA levels showed significant correlation with tumor dimensions (r = −0.184; P = 0.030)." (PMID 25227434, 2014). "SELENBP1 mRNA levels were significantly lower in tumor tissues than in matched normal kidney tissues (P < 0.001) and significantly inversely correlated with pathologic (T-stage and Fuhrman grade) and prognostic variables (progression and cancer-specific death)." (PMID 25227434, 2014). "Patients with ER+ state tumor and low SELENBP1 had poorer survival rates." (PMID 23704933, 2013). "SELENBP1, a member of the selenoprotein family that mediates the transport of selenium in cells, may be related to the proliferation, metastasis, invasion, and therapeutic resistance of tumor cells." (PMID 36718148, 2023). "Therefore, our data strengthened the notion that SELENBP1 levels are associated with inflammatory states and may extend its application into the diagnosis of CAS other than tumor biology." (PMID 36362053, 2022). "Therefore, the low expression of SELENBP1 may contribute to the migration of immune cells in the tumor microenvironment." (PMID 36253721, 2022). "Given the close association between SELENBP1 expression and MTO activity demonstrated here, our MTO assay may allow for a more rapid, simple and quantifiable determination of SELENBP1 levels in tumor tissue than the conventionally used methods of immunoblotting and immunohistochemistry." (PMID 33901808, 2021). "SELENBP1 might play a role in tumor suppression and could be a useful prognostic factor in RCC." (PMID 25227434, 2014). "Selenium-binding protein 1 (SBP1) is a member of an unusual class of selenium-containing proteins that may function as a tumor suppressor in multiple cancer types and whose levels have been shown to be lower in cancers as compared to corresponding normal tissues." (PMID 24163737, 2013). "Tumor tissues exhibited substantial upregulation of TFF1, UBE2C, ITPKA, and IGFBP3, alongside concurrent downregulation of SELENBP1 and SLC34A2, relative to matched normal samples." (PMID 40787454, 2025).
tumor (continued). "Typically, the high level of oxidative stress in cancer cells (usually caused by tumor microenvironment or drug-induced ROS) would lead to cellular apoptosis rather than survival or transformation due to the inhibition of GPx-1 activity, but not its expression, by the upregulated SELENBP1." (PMID 39728443, 2024). "It has been reported that the overexpression of selenium-binding protein 1 (SELENBP1) in HCT116 cells not only suppressed cell proliferation, increased apoptotic cell death, and decreased cell migration, but also inhibited tumor growth and angiogenesis." (PMID 39065104, 2024). "SELENBP1 is identified to be downregulated in cutaneous melanoma influenced by glutathione peroxidase 1 (GPX1) to regulate proliferation and tumor microenvironment." (PMID 36386843, 2022). "SELENOP, SELENBP1, and SOD2 had medium protein expression levels, in both the normal and the tumor cells." (PMID 30469315, 2018). "Among the eight down-regulated genes, one is an oncogene (NEAT1), six are tumor-suppressor genes (ASS1, PTPRD, ISG15, TGFBI, SELENBP1, MEG3) and one gene serves as both an oncogene and tumor-suppressor gene (CDH17)." (PMID 30563222, 2018). "Our tissue array also showed that SELENBP1 expression was dramatically reduced in stage III and ER– tumor tissues." (PMID 23704933, 2013). "IHC showed heterogeneity of SELENBP1 expression within tumors, but there was no certain trend in difference between the center and margin of the tumor." (PMID 37548833, 2023). "In the current study, we uncovered that SELENBP1 was obviously expressed in AT‐II cells for the first time, but SELENBP1 was downregulated in tumor tissues compared with their paired adjacent nontumor tissues." (PMID 37606338, 2023). "One intriguing observation was that SELENBP1 may inhibit EMT, which is one of the key processes mediating tumor metastasis." (PMID 36117772, 2022). "Previous experiments have already demonstrated the anti-tumor roles of HLF and SELENBP1 in LUAD." (PMID 35205284, 2022). "SELENBP1 and CBS are reciprocally regulated during spontaneous differentiation of Caco-2 cells to a colonocyte-like phenotype, thus paralleling their opposing regulation in the tumor tissue of CRC patients." (PMID 36290680, 2022). "In the other 15 (25%) couples of HCC and matched non-tumor (counterpart normal) liver tissues, no obvious difference of SELENBP1 expression was detected." (PMID 32443734, 2020). "Selenium-binding protein 1 (SELENBP1) expression is reduced in various epithelial cancer entities compared to corresponding normal tissue and has already been described as a tumor suppressor involved in the regulation of cell proliferation, senescence, migration and apoptosis." (PMID 29535818, 2018). "In summary, it was speculated that SELENBP1 inhibits GPX1 activity and thus may function as a tumor suppressor only by regulating GPX1." (PMID 29535818, 2018). "SELENBP1 expression is closely related to the prognosis of NPC patients, but also may be a more effective predictor for tumor recurrence or metastasis, and such a conclusion guides our follow-up treatment." (PMID 27583873, 2016). "SELENBP1 expression was down-regulated in HNSCC, but has no associated with T-stage and N-stage of tumor." (PMID 27583873, 2016). "Therefore, reduced SELENBP1 may play a critical role in regulating malignant transformation and cancer progression; further investigations of model organisms to define the biological functions of SELENBP1 and the effects on tumor cells are required to further elucidate these complexities." (PMID 27583873, 2016). "Although there was a trend for a decreased expression of SELENBP1 with increasing tumor size, no statistical difference was seen among four arbitrary size groups: ≤2 cm, 2.1-5 cm, 5.1-8 cm, and ≥8 cm." (PMID 21143902, 2010). "Notably, the expression of SELENBP1 was also decreased in tumor tissues compared with adjacent nontumor tissues by IHC staining and western blotting." (PMID 37606338, 2023).
tumor (continued). "In our study, overexpression of SELENBP1 markedly inhibited the proliferation, migration, and invasion of NSCLC cells in vitro, and further experiments in vivo confirmed that overexpression of SELENBP1 could also inhibit the growth of tumor cells." (PMID 37606338, 2023). "No significant differentially expressed proteins were identified between the two tumour types, however 6 proteins were found to be differentially expressed in the WDLPS component regions of DDLPS compared to ALT, including selenium binding protein 1 (SELENBP1)." (PMID 31722230, 2020). "Using our previous microarray dataset, we determined that the expression of EZH2, RRM1 and FOXM1 was significantly increased in tumor compared with the non-tumor lung tissue and the expression of BTG2, NFIB and SELENBP1 was significantly decreased in the tumor compared to non-tumor." (PMID 30458017, 2018). "All in together, GEO dataset indicated that SELENBP1 expression in HNSCC was downregulated significantly, but there are no new changes with tumor development." (PMID 27583873, 2016). "Therefore, cellular processes resulting from the downregulation of SELENBP1 expression in non-malignant cells may be involved in the early stage of HCC development and may be quite distinct from those in tumor cells." (PMID 32443734, 2020).